RNU1-155P (RNA, U1 small nuclear 155 pseudogene)
Gene: Small nuclear RNA gene on chromosome 1 (148,385,829 to 148,385,963, reverse strand). Ensembl gene ENSG00000252135.
Homologues: Orthologues: chimpanzee U1 (95% identical), macaque U1 (81% identical), dog U1 (70% identical), guinea pig U1 (70% identical), pig U1 (66% identical). Paralogues in human: RNVU1-23 (90% identical), RNU1-89P (77% identical), RNVU1-28 (76% identical), RNU1-1 (76% identical), RNU1-2 (76% identical), RNU1-27P (76% identical), RNU1-28P (76% identical), RNU1-3 (76% identical), RNU1-4 (76% identical), RNVU1-18 (76% identical), RNVU1-29 (76% identical), RNVU1-7 (76% identical), and 134 more.